TNF (tumor necrosis factor)
Diseases named in the same sentence as TNF in open-access papers (continued):
Sharing a sentence is not in itself a finding about the gene and the disease.
liver failure (continued). "Overall, our data suggested that EZH2/H3K27me3 promoted the development of liver failure, which was ameliorated using GSK126 via modulation of TNF and overall inflammation." (PMID 29789597, 2018). "A strong correlation between the circulating levels of TNF-α and those of ammonia was identified in these patients, which suggests a significant relationship between TNF-α and ammonia in patients with liver failure and HE." (PMID 30134917, 2018). "Tumor necrosis factor-alpha (TNF-α) is an important cytokine, which is a key mediator of hepatic apoptosis and necrosis in LPS/D-GaAlN-induced liver failure." (PMID 24963489, 2014). "It is worth mentioning that some inflammatory factors including IL-6, TNF-α, and CD8+T cells, which are induced by bacteria and endotoxins (lipopolysaccharide, LPS) from the gut, are significantly decreased after the BMSCs application in liver failure." (PMID 35122584, 2022). "The low TNF-induced increase of AST and ALT as well as unaltered low bilirubin values (data not shown) demonstrates that hepatic failure was not the cause of mortality in WT mice." (PMID 32410851, 2020). "However, cytokines including tumor necrosis factor (TNF)-α, interferon (IFN)-γ, interleukin- (IL-) 1, IL-6, and IL-10 are believed to be involved in the development of liver failure." (PMID 25892854, 2015). "As the ALF mice that died 9 h (60%, 54/90) after GalN/LPS administration displayed levels of serum biochemical markers and liver morphology consistent with liver failure, we assessed the protective effects of anti-TNF-α IgG and anti-TNF-α R1 antibodies on liver failure 9 h after induction of ALF." (PMID 19772664, 2009). "Indeed, in LPS/D-galactosamine (D-Gal)-induced liver failure, S1P levels were elevated, whilst the expression of SphK1, S1PR1, and S1PR3 was upregulated in the liver, and the levels of serum markers of liver failure, AST and ALT, and the serum cytokines TNF-α, IL-1, and IL-6 were increased." (PMID 39935473, 2025). "Although the exact mechanism is not fully defined, miR-122 expression might modulate TNF-α and affect its function in the liver failure group." (PMID 39666185, 2024). "In the case of liver failure we did not observe negative WE ratios of TNF-α which may indicate a lack of its increased intrahepatic synthesis." (PMID 26090463, 2015). "Therefore, increased TNF-alpha levels in AD-2 may be involved in the absence of liver failure in this group, and, conversely, low TNF-alpha levels could favor the development of liver failure in AD-3 patients." (PMID 30941129, 2019). "In conclusion, the differences in Il-6, TNF-α, HGF, and TGF-β observed in liver donors between the portal and hepatic veins seem to result from their removal by healthy liver, which is absent in liver graft recipients with hepatic insufficiency." (PMID 26090463, 2015).
delirium (92 papers, 2010 to 2026). A disorder characterized by confusion; inattentiveness; disorientation; illusions; hallucinations; agitation; and in some instances autonomic nervous system overactivity. "Chronic low-grade inflammation, marked by elevated interleukin-6 (IL-6) and tumor necrosis factor-alpha (TNF-α), disrupts neurotransmitter balance and impairs brain function, increasing delirium risk." (PMID 39737160, 2024). "A pleiotropic cytokine TNF-a, is associated with several functional pathways including inflammation, necrosis, strong association with cognitive deterioration, apoptosis, and delirium as well." (PMID 39700095, 2024). "Among the pro-inflammatory cytokines, TNFα is upstream of 17 of the 32 CSF delirium-associated proteins, IFNγ has a potential connection to 15/32 CSF proteins, IL-6 is upstream of 10/32 proteins, and IL-10 is upstream of 8/32 proteins." (PMID 37759795, 2023). "We suppose that delirium is associated with increased proinflammatory cytokines (such as IL-6 and TNF-α), which leads to inappropriate activation of peripheral CD4+ T cells and exacerbation of neuroinflammation in the brain, with BBB disruption." (PMID 36118695, 2022). "The pro-inflammatory cytokines, IL-6, TNF-α, IL-1α, IL-1β, have been implicated in delirium-like behavioral changes, such as impaired concentration, diminished motivation, and psychomotor retardation in critically ill patients." (PMID 36030220, 2022). "To further understand the role that inflammation plays in delirium, we measured levels of inflammatory markers, and found that increased IL-6 and TNF-α were significantly associated with delirium development." (PMID 36118695, 2022). "In this respect, previous reports showed that increases in peripheral levels of C-reactive protein (CRP), interleukin-6 (IL-6), CXCL8 (IL-8), and tumor necrotic factor (TNF)-α are associated with the onset of post-operative delirium." (PMID 35641947, 2022). "Elevated plasma concentrations of TNF-α, IL-6 and IL-8 were reported to be associated with delirium." (PMID 34425856, 2021). "Our previous prospective study conducted among cardiac surgery patients revealed that raised levels of IL-2 and TNF-α measured in the postoperative period are associated with the development of delirium among CABG surgery patients." (PMID 33918634, 2021). "sTNFR1 is a receptor for Tumor Necrosis Factor-α and has previously been observed to be associated with delirium in ICU cohorts." (PMID 31856187, 2019). "Multivariate logistic regression analysis demonstrated the significant association of delirium with TNF-α and the receiver operating characteristics analysis for the predictive value of delirium showed an area under the curve of 0.851." (PMID 29137628, 2017). "Based on the association of neuroinflammation with delirium, the levels of IL-1β, IL-8 and TNF-α in CSF were measured before and after WAY-100635 treatment." (PMID 27760517, 2016). "Extended with the biomarkers TNF-α, IL-6, IL-18, IL-1ra, and IL-10, the 10 best biomarkers associated with delirium (all P < 0.10) were then entered into a multivariate logistic regression analysis." (PMID 22206727, 2011). "In patients with delirium, it was demonstrated that pro-inflammatory cytokines, such as IL-6, IL-1α, IL-1β, and TNF-α, are associated with delirium-like behavioral disturbances, such as diminished concentration, altered motivation, and decreased psychomotor activities." (PMID 41156174, 2025). "Severe delirium was associated with rising trends in the serum levels of inflammatory markers, e.g., TNF-Alpha (p = 0.084 at 24 h and p = 0.087 at 72 h), Interleukin-8 (p = 0.032 at 24 h and p = 0.082 at 72 h), and Lipocalin-2 (p = 0.004 at 24 h and p = 0.078 at 72 h) in all studied subjects." (PMID 38136021, 2023). "TNF-α and IL-1β are two prototypical cytokines hardwired to NF-κB signaling and are implicated in the development of age-related postoperative complications including delirium and postoperative cognitive dysfunction." (PMID 27493629, 2016).
delirium (continued). "Although elevated plasma TNFα levels are associated with increased blood–brain barrier permeability and neuronal apoptosis, we could not demonstrate any association between plasma TNFα levels and delirium in our cohort." (PMID 24886875, 2014). "Dexmedetomidine demonstrated a dose-dependent effect on TNF-α modulation, delirium incidence, and opioid consumption; however, its influence on IL-6 levels and extubation time was less pronounced." (PMID 40283079, 2025). "Peripheral inflammation is a well-established trigger of delirium, and IL-1, IL-1β, IL-6, IL-8, tumor necrosis factor (TNF), and prostaglandin E2 (PGE2) stimuli trigger tissue macrophage and blood monocyte activation and secretion of inflammatory mediators." (PMID 41459337, 2025). "Whereas, i.c.v. administration of IL‐1α, TNF‐α, and C1q can increase their immunoactivity and mimic delirium‐like behavior in the young mice, and intraperitoneal injection of Ex‐4 attenuated such changes." (PMID 38155547, 2024). "Hypotension also triggers inflammatory responses, releasing cytokines like IL-6 and TNF-α, contributing to delirium." (PMID 39090732, 2024). "A trend toward elevated TNF-α can be similarly observed in patients who develop delirium in the ICU." (PMID 38379709, 2024). "Several studies have demonstrated a link between proinflammatory cytokines (C-reactive protein, interleukin-6, and tumor necrosis factor-alpha) and delirium." (PMID 39604840, 2024). "Among the unique proteins, we focused on the top 13 most investigated proteins (IL-6, CRP, IL-8, S100B, IL-10, TNF-a, IL-1b, Cortisol, MCP-1, GFAP, IGF-1, IL-1ra, and NFL) that are significantly associated with delirium." (PMID 39700095, 2024). "Our previous study showed a probable correlation between elevated endogenous DA levels and suppressed TNF-α expression in an LPS-induced delirium rat model." (PMID 38623339, 2024). "In oncology, a cross-sectional relationship has been established between blood BDNF and TNF-α levels with delirium." (PMID 38928583, 2024). "Inflammatory markers such as interleukin-1B (IL-1B), interleukin-6 (IL-6), and tumor necrosis factor-a (TNF-a) have been observed to be elevated in patients with delirium." (PMID 38263028, 2024). "IL-6, IL-8, IL-10, IL-18, TNF-α, and chemokines (CCL2, CCL3, CXCL1, and CXCL10) have also been reported to be elevated in ICU delirium patients and are associated with delirium severity." (PMID 39308447, 2024). "We measured the expression of COX-2, IL-1β, IL-6, and TNF-α in the blood using ELISA on both the day of delirium onset (D1) and the 5th day after delirium onset (D5)." (PMID 38902693, 2024). "Overall, pooled analysis showed a significant increase in some serum biomarkers (i.e., CRP, TNF-α, and IL-6) of patients who developed delirium (OR = 1.88, 95% CI 1.01 to 1.637; I2 = 76.75%)." (PMID 37251808, 2023). "The additional measurement of interleukin (IL)-6, IL-8, IL-10 and tumor necrosis factor-α increases the accuracy to predict delirium and an unfavorable outcome." (PMID 37744876, 2023). "Inflammatory mediators such as IL-1B, IL-6, IL-8, IL-10, TNF-alpha, and C-reactive protein (CRP), have all shown associations with delirium." (PMID 36803215, 2023). "In septic encephalopathy, coma patients (n = 18) displayed higher IL-6, TNF-α and IL-12 plasma concentrations than delirium patients (n = 64)." (PMID 37744876, 2023). "Given the correlation between neuroinflammation and postoperative delirium, we took TNF-α as an inflammatory marker to elucidate the plausible mechanism." (PMID 34979943, 2022). "There is an increased systemic production of interleukin-1 α (IL-1α), IL-1β, IL-6, IL-10, and tumor necrosis factor α (TNF-α), which are implicated in the pathogenesis of delirium." (PMID 36030220, 2022). "Comparing the findings from this review to other causes of delirium makes clear that in delirium from other causes mostly biomarkers regarding inflammatory pathways are involved (e.g., IL-6, CRP, Corsitol, TNF-alpha)." (PMID 36230916, 2022).
delirium (continued). "For example, it was shown that DNAm levels in several CpG sites on the TNF gene were negatively correlated with age only in delirium subjects." (PMID 34887385, 2021). "Recent studies have demonstrated associations between traditional inflammatory markers and delirium, such as C-reactive protein (CRP), interleukin (IL)-6, IL-8, IL-2, and tumor necrosis factor (TNF)." (PMID 34034650, 2021). "This study is based on the findings that dexmedetomidine, an α2-agonist, reduces the release of TNF-α and prevents both delirium and hepatocyte injury in human liver transplantation." (PMID 34451922, 2021). "Recent work correlated markers of systemic inflammation and those of astrocyte and glial cell activation (IL-6, IL-8, IL-10, TNF-α, C-reactive protein and S-100β levels) with longer duration of delirium, more severe delirium and higher in-hospital mortality." (PMID 32443606, 2020). "These are strong TNF inducers in bacterial infections and trauma respectively, well-recognized potential inducers of delirium." (PMID 29725287, 2018). "In fact, relationship between direct measurement of TNF-alpha level and delirium has been controversial." (PMID 30405391, 2018). "After correction for monocyte count, patients with delirium had reduced LPS-induced TNFα, IP-10, IL-1β, IL-6, and IL-12 release." (PMID 29669581, 2018). "Excessive release of proinflammatory cytokines such as TNF-α, IL-1, IL-6, and IL-8 during systemic inflammation can affect brain functions and promote the development of delirium." (PMID 24337734, 2014). "The study did not include other relevant biomarkers of systemic or neuroinflammation (e.g., interleukin-6, TNF-α, or S100B protein), which could have provided a broader mechanistic understanding of the inflammatory contribution to delirium." (PMID 41303282, 2025). "Additionally, common cytokine imbalances in AID patients, especially the elevation of pro-inflammatory factors such as IL-1β, IL-6, TNF-α, have been found to be closely related to the occurrence of delirium." (PMID 40740958, 2025). "Only 6 studies were eligible for the meta-analysis, pooled results showed a significant increase in some serum biomarkers (C-reactive protein [CRP], tumour necrosis factor alpha [TNF-α] and interleukin-6 [IL-6]) among patients with delirium (odds ratio = 1.88, 95% CI 1.01 to 1.637; I2 = 76.75%)." (PMID 37251808, 2023). "A systematic review of animal experiments indicated that activation of microglial was concerned with the elevated levels of IL-1β, TNF-α, and Toll-like receptors, and could contribute to delirium." (PMID 36455873, 2022). "The first major finding of this study is that delirium and/or the severity of delirium symptoms are significantly associated with the IRS/CIRS ratio, namely positively with M1 (i.e. IL-6, CXCL8 and TNF-α), Th1 and Th17 activation and T cell growth (positively), and inversely with IL-4 and sIL-1RA." (PMID 35641947, 2022). "Consistent with our assumption, the patients in the PBA group exhibited lower incidence of delirium and level of TNF-α, indicating that paravertebral block analgesia could alleviate the inflammatory response." (PMID 34979943, 2022). "Cunningham made essentially the same TNF argument about the pathogenesis of delirium." (PMID 29725287, 2018). "Our findings support that acute systemic inflammatory TNF-α can sufficiently induce acute dysfunction in a cognitive task reliant on attentional and working memory function; two key cognitive domains were impaired in delirium." (PMID 29137628, 2017). "It is significant that in this model of acute systemic inflammation TNF-α alone is sufficient to induce acute dysfunction in a cognitive task reliant on attentional and working memory function, two key cognitive domains impaired in delirium." (PMID 27633985, 2017). "Interestingly, inflammatory mediators (for example, interleukin-1, interleukin-6, and tumor necrosis factor alpha (TNF-α)) can contribute to delirium." (PMID 25189637, 2014).
delirium (continued). "In mice, tumor-necrosis factor (TNF)-α is a mediator of apoptotic cellular death in the brain and may therefore be causally associated with the development of delirium in patients with severe inflammation." (PMID 22206727, 2011). "For example, a systematic evaluation of animal experiments has shown that microglia activation is associated with elevated levels of IL-1β, TNF-α, and Toll-like receptors (activated microglia release cytokines and chemokines, such as IL-1β, IL-6, and TNF-α), and may lead to delirium." (PMID 40661144, 2025). "The present study revealed the potential possibility that B cell, memory B cell subset, and TNF-related molecules may be involved in the development of delirium due to peripheral inflammation, which can provide clues for further investigation of delirium prevention and treatment strategies." (PMID 38379709, 2024). "In summary, the MR analysis indicated that there may not be a causal association between delirium and the following factors: TNF-α, CRP, IL-1α, IL-1β, IL-2, IL-6, sIL-6Rα, soluble gp130, and IL-8." (PMID 37649721, 2023). "Thus it seems logical that, in the context of post-surgical delirium, dexmedetomidine is likely to be acting by inhibiting TNF production, its efficacy in these two studies determined by the timing of its administration in relation the onset of the surgical event." (PMID 29725287, 2018). "Likewise, the association between delirium and higher IL-1, IL-6 and TNF-α plasma levels was not confirmed." (PMID 26106326, 2015). "We previously found that delirium was associated with IL-8 (odds ratio, 9.0; 95% confidence interval, 1.8 to 44.0) and IL-10 (odds ratio, 2.6; 95% confidence interval, 1.1 to 5.9) but not with TNFα in inflamed ICU patients." (PMID 25042374, 2014). "Significant differences between the delirium and non-delirium groups were observed in terms of age, TBI classification, sleep duration, CRP levels, TNFα levels, pain scores, self-efficacy, and insomnias (P < 0.05)." (PMID 39554848, 2024). "We have summarized the 13 most studied proteins (IL-6, CRP, IL-8, S100B, IL-10, TNF-a, IL-1b, Cortisol, MCP-1, GFAP, IGF-1, IL-1ra and NFL) about delirium." (PMID 39700095, 2024). "We previously reported that the onset and severity of delirium are significantly correlated with IRS activation, including increased M1 (with IL-6, IL-8, and TNF-α), Th1, Th17, and T cell growth profiles." (PMID 38379706, 2024). "This study evaluated the effect of nine genetically predicted inflammatory factors (TNF-α, CPR, IL-1α, IL-1β, IL-2, IL-6, sIL-6Rα, Soluble gp130, and IL-8) on delirium." (PMID 37649721, 2023). "Ritter and colleagues studied TNFα, soluble TNF receptor (STNFR)-1, STNFR2, IL-1β, IL-6, IL-10 and adiponectin in systemic inflamed patients in relation to delirium." (PMID 25042374, 2014). "In recent evidence, the median level of serum TNF-α (p = 0.048) was significantly higher in patients with delirium after cardiac surgery than in those who did not develop delirium after surgery." (PMID 38379709, 2024). "Interestingly, we conducted a meta-analysis with IL-6, TNF-α, and CRP, which were the most investigated biomarkers, and we found that they were statistically significant predictors of delirium." (PMID 37251808, 2023). "In the current research, pre-infusion of HS reduced the levels of IL-6, TNF-α and S100β compared with normal saline group, which is in accordance with prior studies that found higher levels of S100β in patients with delirium than in patients without delirium." (PMID 38082215, 2023). "The results of this MR analysis did not support that peripheral TNF-α, CRP, IL-1α, IL-1β, IL-2, IL-6, sIL-6Rα, soluble gp130, and IL-8 were causally associated with delirium." (PMID 37649721, 2023). "Although current evidence does not favour the use of any particular biomarker, serum CRP, TNF-α, and IL-6 were the most consistent biomarkers of delirium in older patients." (PMID 37251808, 2023).